PDCD1 (programmed cell death 1)
Diseases named in the same sentence as PDCD1 in open-access papers (continued):
Sharing a sentence is not in itself a finding about the gene and the disease.
ovarian clear cell cancer (1 paper, 2022). An invasive malignant neoplasm that arises from the ovary and is characterized by a predominance of clear and hobnail malignant epithelial cells. "Here, we present the case of a patient with recurrent ovarian clear cell carcinoma (OCCC) who failed to respond to multiline chemotherapy and target therapy but achieved an immune complete response (iCR) with programmed cell death 1 (PD-1) inhibitor treatment." (PMID 36275748, 2022).
ovarian serous cystadenocarcinoma (1 paper, 2025). A malignant serous cystic epithelial neoplasm arising from the ovary. "In ovarian serous cystadenocarcinoma (OV), the PDCD1 expression levels showed no significant statistical difference between tumor and normal tissues." (PMID 40149458, 2025).
pancreatitis (1 paper, 2024). Inflammation of the pancreas. "This review discusses the relationship between ICIs and their effects on the pancreas, including the incidence of pancreatitis, immunotherapy, programmed cell death 1 (PD-1) receptors, driver mutations, programmed death ligand 1 (PD-L1), and immune-related adverse events." (PMID 39347217, 2024).
Salmonella Infections (1 paper, 2025). Infections with bacteria of the genus SALMONELLA. "Cluster 5 was defined by the expression of genes like Tox, Cxcr5, and Pdcd1, consistent with T follicular helper-like cells, which are typically localized in colonic patches or isolated lymphoid follicles and regulate IgA production during Salmonella infection." (PMID 40924026, 2025).
sialadenitis (1 paper, 2022). Sialadenitis is an infection of the salivary glands. "The NOD.Pdcd1-/- mouse, which presents a rapid onset of both autoimmune diabetes and sialadenitis, can thus be used to study polyautoimmunity." (PMID 35572553, 2022). "Rather than developing autoimmune diabetes, the NOD-H2b/b mice develop SS, whereas the NOD-H2b/b.Pdcd1-/- female mice are polyautoimmune; they develop spontaneous peripheral polyneuropathy, sialadenitis, pancreatitis, vasculitis, and gastritis." (PMID 35572553, 2022). "Sialadenitis is also accelerated and more severe, with significantly greater pathological scores at 6 weeks of age in NOD.Pdcd1-/- relative to NOD mice." (PMID 35572553, 2022).
silicosis (1 paper, 2025). Silicosis is a respiratory disease caused by breathing in (inhaling) silica dust. "In addition, Lilr4a, Lilr4b, and Tnfsf18 were significantly up-regulated in the early and middle stages of silicosis, while Pdcd1, Ctla4, and Tigit were significantly up-regulated in the middle and late stages of silicosis." (PMID 39498466, 2025).
thymic carcinoma (1 paper, 2019). Thymic carcinoma (TC) is a type of thymic epithelial neoplasm characterized by a high malignant potential. "We examined the clinical significance of EMT, tumor‐infiltrating lymphocytes expressing the immune checkpoint protein, programmed cell death 1 (PD‐1 + TILs), and the expression of PD‐1 ligand 1 (PD‐L1) in thymic carcinoma (TC)." (PMID 30600651, 2019).
tongue cancer (1 paper, 2021). A malignant neoplasm affecting the tongue. "The extract significantly reduces the expression of pro-inflammatory molecules s100a9, interleukin 23 subunit alpha (IL23a), interleukin 1 beta (IL1β) and immune checkpoint gene PDCD1/programmed cell death-1 (PD1) during tongue cancer prevention." (PMID 34765739, 2021).
ulcers (1 paper, 2024). "The expression of programmed cell death-1 (PD1) protein in infected gastric epithelial cells positively correlated with vacA m1/m2 in patients with gastritis and ulcers, but inversely correlated with vacA s1/m1." (PMID 39857645, 2024).
uterine corpus endometrial carcinoma (1 paper, 2022). A endometrial carcinoma (disease) that involves the body of uterus. "At last, a higher PDCD1 gene expression was linked to lower Log2HR in UVM, LGG, kidney renal papillary cell carcinoma (KIRP), and ESCA, but high Log2HR for HNSC, SKCM, uterine corpus endometrial carcinoma (UCEC) and BRCA." (PMID 36354714, 2022).
venereal warts (1 paper, 2024). "In contrast, skewing of HPV-specific T cells from an effector Th1 to a Th2 profile or increased expression of programmed cell death 1 in infiltrating CD8+ T cells in patients with venereal warts may suggest suppressed effector immunity." (PMID 38900571, 2024).
vulvar carcinoma (1 paper, 2024). "Furthermore, a phase 2 study of pembrolizumab, an anti-programmed cell death 1 monoclonal antibody, resulted in an objective response rate of 10.9% in patients with advanced vulvar cancer." (PMID 38882968, 2024).
ZIKV infection (1 paper, 2022). "ZIKV infection also resulted in the upregulation of Programmed cell death protein 1 (PDCD1), a gene implicated in immune suppression and cell death." (PMID 35304593, 2022).
tumor (2,265 papers, 2011 to 2026). "In MC38 tumours, Treg cells show increased Pdcd1 expression, depending on SREBP activity linked to mevalonate metabolism‐driven protein geranylgeranylation." (PMID 40785042, 2025). "The binding of programmed cell death ligand-1 (PD-L1) on RCC tumour cells and programmed cell death-1 (PD-1) on anti-tumour T cells cause downregulation of cytotoxic killing activity and exhaustion of T cells, leading to an immune escape phenomenon." (PMID 40555768, 2025). "Tumor-associated LECs take on an immunosuppressive phenotype expressed by immune-inhibitory molecules, in which the programmed cell death 1 (PD-1) and its ligand PD-L1 are upregulated in tumor-associated lymphatic vessels." (PMID 41511312, 2025). "Downregulation of DEC2 in macrophages increases PDCD1 expression, encoding PD-1, which in turn enhances tumor cell clearance by anti-PD-1 therapy." (PMID 40399946, 2025). "ICIs target cytotoxic T-lymphocyte-associated antigen-4 (CTLA-4) or programmed cell death-1 (PD-1)/programmed cell death-ligand 1 (PD-L1) pathways to disrupt tumor immune evasion." (PMID 40881122, 2025). "These cells represented a relatively small proportion of the total T cell pool, and showed expression of ITGAE (encoding CD103), CXCL13, ENTDP1, PDCD1 and other checkpoint molecules consistent with previous antigen exposure and tumour reactivity." (PMID 41115454, 2025). "Immune checkpoint inhibitors (ICIs) against cytotoxic T‐lymphocyte‐associated antigen 4 (CTLA‐4) and programmed cell death 1 (PD‐1) reactivate immune cells and have shown promising anti-tumor responses in a subset of advanced melanoma patients." (PMID 39751902, 2025). "In this trial, they deleted the TRAC and TRBC genes, which encode components of the endogenous T cell receptor, and the PDCD1 gene, which encodes the PD-1 protein, from the patients’ T lymphocytes to enhance anti-tumor immunity." (PMID 39281673, 2024). "CSF1R+PDCD1+ tumour‐associated macrophages (TAMs) exhibit strong signal communication with MAIT cells at the tumour edge." (PMID 39350478, 2024). "High expression levels of FAM202B correlated with increased resistance to sunitinib and enhanced responsiveness to immunotherapy, as evidenced by associations with tumour mutation burden, PDCD1, CTLA4 and TIDE scores." (PMID 39198940, 2024). "PDCD1 inhibitors were associated with the upregulation of T cells and interferon-gamma-related gene expression and enhanced both local and systemic anti-tumor immune responses." (PMID 38460946, 2024). "PDCD1 (PD-1) was strongly associated with tumor mutation burden (TMB), microsatellite instability (MSI), and immune cell infiltration, and it can be used as a prognostic marker in several cancer types." (PMID 36843949, 2023). "In Tox-deficient tumor-infiltrating T cells, a large fraction of gene loci for inhibitory receptors like Pdcd1, Havcr2 and Tigit are revealed to be inaccessible." (PMID 37398674, 2023). "It was discovered that patients with high m6A scores had longer survival, lower tumor mutation loads, and low PD-L1/PDCD1/CTLA4/TAG3 expression level." (PMID 35419413, 2022). "In particular, each single gene expression had little contribution to the higher or lower risk of prognosis, such as PDCD1 (PD-1, hazard ratio: 0.99), which indicated the complexity of the tumor immune microenvironment." (PMID 35832540, 2022). "For example, programmed death-ligand 1 (PD-L1)/programmed cell death-1 (PD-1) levels, tumor mutational burden (TMB), and CD8 T cells can be used to assess the efficacy of immunotherapy." (PMID 35756601, 2022). "It has previously been reported that increased tumor mutation burden is associated with clinical efficacy of inhibition of programmed cell death 1 (PDCD1, also known as PD-1), i.e. anti-PD-1 therapy." (PMID 34870316, 2022).
tumor (continued). "Exosomes secreted by GC cells can guide monocytes into M2-characterized programmed cell death 1 (PD-1)-positive tumor-associated macrophages, upregulating the secretion of IL-10 and thus affecting the function of CD8+T cells." (PMID 36230816, 2022). "PDCD1 (encoding PD-1 protein) is a key mediator in regulating T-cell activation and tumor antigen priming of TIME, also closely interlinked with TMB." (PMID 36226174, 2022). "Three classes of CD4+ T cells were identified via SCS, and it was found that CD4_1 upregulates TIGIT expression in tumors, CD4_2 expresses PD-1 (encoded by PDCD1) exclusively in tumors, and CD4_3 showed tumor-specific TIGIT and CD96 expression." (PMID 35785171, 2022). "CTLA-4 and PDCD-1 are important immune checkpoint proteins that are associated with tumor immune escape." (PMID 35769911, 2022). "This involves the use of inhibitory antibodies capable of specifically blocking two receptors that inhibit the anti-tumor immune response of T lymphocytes: PD-1 (Programmed cell death 1) and CTLA-4 (Cytotoxic T-Lymphocyte-Associated protein 4)." (PMID 36286442, 2022). "Immune checkpoint molecules, such as cytotoxic T lymphocyte associated antigen-4 (CTLA-4) and programmed cell death-1 (PD-1) on the T cell surface, play a critical role in tumor immune escape." (PMID 35565217, 2022). "This is concordant with the notion that tumor-infiltrating CD8+ T cells exhibit enhanced expression of programmed cell death protein 1 (PDCD1), an immune-inhibitory receptor associated with an “exhausted” CD8+ T-cell phenotype." (PMID 34439112, 2021). "A high rate of de novo somatic mutations leads to high levels of neoantigens, causing abundant tumor-infiltrating lymphocytes, which are counterbalanced by the increased expression of immune checkpoint molecules, such as PDCD1 and CD274." (PMID 34680073, 2021). "In other solid tumors, immune checkpoint blockade targeting inhibitory receptors expressed on T cells such as cytotoxic T lymphocyte–associated protein 4 (CTLA-4) or programmed cell death 1 (PD-1) elicits clinical improvement and tumor regression." (PMID 33232299, 2021). "PDCD1 was shown to inhibit phagocytosis by tumor-associated macrophages, thus providing anti-tumor immunity." (PMID 34100771, 2021). "The GCAT haplotype, exhibiting lower PDCD1 mRNA expression in tumour biopsies and a fully active IFNλ4 protein, associated with HCC in our series." (PMID 32937024, 2021). "This antibody is directed at cytotoxic T lymphocyte-associated antigen-4 (CTLA-4), programmed cell death 1 (PD-1), and programmed cell death 1 ligand 1 (PD-L1) receptors; it initiates immune cell function, and normalizes the tumor microenvironment." (PMID 33282564, 2020). "Binding of PD-L1 on tumor cells to PD-1 receptors (encoded by the PDCD1 gene) on T cells blocks anti-tumor T cell activity and thus allows tumor cells to evade the host immune surveillance." (PMID 32275681, 2020). "The well-known immune checkpoints inhibitors (ICIs) targeting the programmed cell death 1 (PD-1) or the cytotoxic T-lymphocyte associated antigen 4 (CTLA-4) checkpoints have demonstrated the potential for relatively tumor-specific immune disinhibition." (PMID 32168869, 2020). "Cytotoxic T lymphocyte-associated antigen 4 (CTLA4) and programmed death-1 (PD-1; encoded by the PDCD1 gene) represent crucial immune checkpoints, the blockade of which can potentiate anti-tumour immunity." (PMID 33225954, 2020). "At the transcriptional level, high expression of PDCD1 within the tumor was significantly associated with improved DFS (HR 0.38; P = 0.027)." (PMID 30728081, 2019). "Tumor responses to these therapies are mediated mainly by anti-tumor T cell immunity previously blocked by CTLA-4 (cytotoxic T lymphocyte-associated protein 4) or PD-1 (programmed cell death 1)." (PMID 31602274, 2019).
tumor (continued). "Accumulating evidence indicates that MSI and MMR deficiency with high tumor mutational load can predict a response to the anti-PDCD1 antibody in metastatic CRC (mCRC)." (PMID 29361689, 2018). "In a therapeutic context, the presence of germline variants in PDCD1 or tumor overexpression of the receptor may predict responses to inhibitors such as nivolumab or pembrolizumab." (PMID 40869918, 2025). "The cell surface protein PD-1 (encoded by PDCD1), long known to be associated with immune exhaustion when expressed on T-cells, has recently been proposed to also be a tumor suppressor expressed on some tumor cells." (PMID 39136002, 2024). "Both metabolic stresses of T cells driven by TME fuel depletion and increased expression of inhibitory receptors like programmed cell death-1 (PD-1), cytotoxic T lymphocyte-associated protein 4 are the essential factors that result in tumor-infiltrating CD8+ T cells exhaustion." (PMID 38812059, 2024). "Immune checkpoint inhibitors (ICIs) targeting cytotoxic T lymphocyte-associated protein 4 (CTLA4), programmed cell death-1 (PD-1), and programmed cell death ligand-1 (PD-L1) have shown promising efficacy in certain tumor types, leading to their entry into the clinic." (PMID 38466449, 2024). "The programmed cell death 1 protein (PD-1)/programmed cell death ligand 1 (PD-L1) axis plays a crucial role in tumor immunosuppression, while the cancer-associated fibroblasts (CAFs) have various tumor-promoting functions." (PMID 37668710, 2023). "associated the low PDCD1 levels in the tumor with low lymphocytic infiltration." (PMID 36825029, 2023). "The first group consists of ICIs inhibiting cytotoxic T lymphocyte-associated protein 4 (CTLA-4) on T cells, the second one is related to programmed cell death 1 (PD-1) receptor on lymphocytes, and the third group is linked to programmed cell death ligand 1 (PD-L1) on tumor cells." (PMID 37055532, 2023). "The immune response of CD8+ immune cells and the PDCD1 tumor association may be the targets of ICI molecules, which can also indicate the prognosis of cancer." (PMID 38248311, 2023). "One of the many mechanisms underlying tumor immune escape is mediated by programmed death receptor 1 (PD-1), a cell surface receptor encoded by the PDCD1 gene that is expressed on different immune cells and acts as a receptor for programmed death ligands (PD-L1 and PD-L2) expressed on tumor cells." (PMID 37316937, 2023). "A significant advancement in precision oncology was the tissue-agnostic FDA approval of the programmed cell death-1 (PD-1) inhibitor pembrolizumab for the treatment of any tumor with mismatch repair deficiency (MMRd) or high microsatellite instability (MSI-H), regardless of the tissue of origin." (PMID 37174018, 2023). "Immune checkpoint blockers (ICBs), such as cytotoxic T lymphocyte-associated antigen 4 (CTLA-4) and programmed cell death 1 (PD-1) inhibitors, exert revolutionary effects on several tumors, while the efficacy seems to be closely related to the tumor immune microenvironment (TIME)." (PMID 35898512, 2022). "CTLA-4 and PDCD-1 are two critical proteins associated with tumor immune escape." (PMID 35769911, 2022). "Then, he was submitted to a cycle of anti-programmed cell death-1 (PD-1) therapy after failure of Crizotinib and eventually acquired resistance despite of the high expression of programmed death ligand-1 (PD-L1) and tumor mutational burden (TMB) status." (PMID 35739536, 2022). "In particular, ICIs, which are antibodies against cytotoxic T lymphocyte-associated protein 4 (CTLA-4), programmed cell death 1 (PD-1), or its ligand PD-L1, have been successfully applied clinically for solid tumors, relieving the inhibitory effect of the tumor microenvironment on T cells." (PMID 36238278, 2022).